INS (insulin)
Diseases named in the same sentence as INS in open-access papers (continued):
Sharing a sentence is not in itself a finding about the gene and the disease.
Insulin resistance (continued). "The insulin signal cascades, which include PKB/Akt through PI3K and mTOR, stimulate S6K1, resulting in a negative feedback, which may cause insulin resistance." (PMID 22761194, 2012). "On SR5 relative to B1, glucose (F1,168 = 25.3, p<0.001) and insulin (F1,168 = 12.2, p<0.001) were increased, triglycerides (F1,168 = 7.5, p = 0.007) fell and there was no significant change in fasting homeostatic model assessment (HOMA) determined insulin resistance (F1,168 = 1.3, p = 0.18)." (PMID 22844441, 2012). "In fact, IMCL may constitute the missing link between obesity and development of insulin resistance, since overweight individuals can improve their insulin sensitivity with exercise training, even in the absence of significant changes in total body adiposity." (PMID 22359625, 2012). "The present study suggests that fasting serum C‐peptide levels were a better predictor of cardiovascular and overall death than fasting serum insulin and its derived measures of insulin resistance in a nationwide sample of nondiabetic adults between 40 and 74 years of age." (PMID 23316320, 2012). "It is also shown that chronically elevated plasma FFA levels cause insulin resistance, and lowering elevated plasma FFA levels overnight normalizes insulin sensitivity in obese nondiabetic subjects and significantly improves insulin sensitivity in obese diabetic patients." (PMID 22675349, 2012). "Similarly, ghrelin hyperglycemic effect have been reported to be independent of an insulin resistance induction as evidenced by insulin and glucose tolerance tests after ghrelin administration." (PMID 23162532, 2012). "Although HOMA and insulin levels were not different from controls in the non-diabetic survivors, we show that radiotherapy involving both head and tail of the pancreas influenced the occurrence of dyslipidemia and insulin resistance significantly." (PMID 23251703, 2012). "Resistance to insulin-mediated glucose disposal is distributed continuously through the general population, and we have no criterion with which to identify a participant as being insulin resistance." (PMID 23020992, 2012). "The fact that serum levels of activins or follistatin are not clearly predictive of T2D or insulin resistance in individual patients could be due to the complicated roles of activin A and B in the regulation of glucose and insulin metabolism." (PMID 23304117, 2012). "Therefore, the defects in the insulin signaling pathway observed at the protein level, including Munc18c, PKCζ, phospho-PKCζ, and Syntaxin-4 in PCOS patients with insulin resistance, could lead to impaired glucose uptake." (PMID 22390153, 2012). "Epidemiological studies indicate a direct relation of dietary SFA with the incidence of insulin resistance or T2DM, whereas replacing SFA by MUFA may improve insulin sensitivity and beneficially influence blood pressure, low-density lipoprotein (LDL) cholesterol, and triacylglycerols." (PMID 24278690, 2012). "By contrast, light to moderate insulin resistance is compensated for by increased insulin secretion, or moderately increased insulin secretion does not accompany insulin resistance, both of which lead to increased insulinotropic action and possibly increased serum amylase." (PMID 22748134, 2012). "Other evaluation methods of insulin resistance, such as the HOMA-IR of minimal model and steady-state model, Bennett index, Li Guangwei index, insulin sensitivity check index (QUICKI), and fasting glucose and insulin ratio (G/I), are more complex, time-consuming, and expensive." (PMID 22792101, 2012). "However, plasma insulin levels were increased, therefore suggesting the development of insulin resistance, even in the absence of TNFα." (PMID 23125848, 2012). "Direct effects of NRTIs and NNRTIs on insulin sensitivity have not been demonstrated, but these classes may contribute to insulin resistance indirectly through changes in body fat distribution." (PMID 21876813, 2012).
Insulin resistance (continued). "In fact, it seems as if in the presence of insulin resistance T3 may not be able to act as fully as in the case of an unopposed insulin signal, such as when metabolically effective exogenous insulin levels are attained." (PMID 22973308, 2012). "However, while only one third of individuals with insulin resistance will ultimately develop type 2 diabetes, many others do not because their β-cells are able to respond adequately to the increased demand for insulin." (PMID 22929089, 2012). "One can speculate the rapid restoration of euglycemia was enabled by the ablation of insulin resistance and ablation of the pro-inflammatory invasive insulitis enabling dysfunction but not destroyed beta cells to resume insulin production." (PMID 22606220, 2012). "The observed negative effects of high H2O2 concentrations on insulin signal transduction are consistent with our previous report, which showed that mitochondria-derived ROS induce insulin resistance in H4IIEC hepatocytes treated with palmitate by activating JNK." (PMID 22102892, 2011). "Insulin resistance is common in septic conditions, resulting in a relative lack of insulin in vivo." (PMID 21639905, 2011). "As already reported, we found that in insulin resistance conditions, insulin treatment does not induce NO production; chronic treatment with sildenafil improves NO production in basal conditions as well as in insulin resistance conditions in e-NOS-dependent manner." (PMID 21297971, 2011). "The miR-278 mutants also had high circulating sugar levels despite elevated insulin production, which suggested lack of miR-278 may lead to insulin resistance." (PMID 21506921, 2011). "However, QUICKI and insulin action do not correlate highly, particularly in individuals with mildly insulin resistance, impaired glucose tolerance or elderly patients with poorly controlled T2DM." (PMID 21251282, 2011). "In the current study, no additional effect of rosiglitazone on insulin and insulin resistance could be observed, stressing the highly beneficial effects of lifestyle intervention, overshadowing the possible effect of rosiglitazone on these parameters." (PMID 22035351, 2011). "Moreover, the lack of adipose PGC-1α neither induces insulin resistance in mice nor it precludes the insulin-sensitizing effects of rosiglitazone." (PMID 22087241, 2011). "In that study, it was not reported whether there was a change in insulin sensitivity in these subjects during this intervention; however it can be speculated that overfeeding promotes insulin resistance in the brain to diminish brain activity." (PMID 21589921, 2011). "Adjusting for obesity in studies of insulin resistance may not be appropriate, because of its collinearity with insulin." (PMID 21911326, 2011). "Interestingly, NT-proCNP in critically ill patients was indeed correlated with endogenous insulin levels (C-peptide) as well as serum resistin and retinol-binding protein 4, two mediators of insulin resistance (data not shown)." (PMID 21281508, 2011). "It is possible that the peripheral hyperinsulinemia in the HFD animals in this study may induce increased entry of insulin into the brain, which, in the absence of brain insulin resistance, results in a reduction in the levels of phosphorylated tau." (PMID 21347323, 2011). "Two theories have been proposed to explain the development of insulin resistance in IUGR: the first is the foetal reprogramming due to thrifty phenotype hypothesis; the second is the establishment of an insulin-resistant genotype independently of intrauterine environment." (PMID 22190925, 2011). "Obesity is associated with chronic low-grade inflammation, and this is believed to be one of the major contributors to the development of insulin resistance, which is an early event in obesity and leads to type 2 diabetes when the pancreas fails to keep up with increased demand for insulin." (PMID 22035457, 2011).
Insulin resistance (continued). "Although insulin resistance is likely to account for liver and muscle damage, somewhat surprising is that the apparently less severe tissue fat infiltration in pair-fed mice occurred without concordant restoration in insulin sensitivity." (PMID 21151924, 2010). "In addition to insulin, insulin-like growth factor-1 (IGF-1) is another substance that lowers serum levels of glucose in both rats and humans and has even the capability of doing so in patients with severe insulin resistance." (PMID 20414467, 2010). "Intensive insulin therapy to treat hyperglycaemia in critically ill patients, which may be due to illness-related insulin resistance and not to previously known diabetes, appears to improve morbidity and mortality’." (PMID 21189875, 2010). "HOMA-IR may also serve as a surrogate measure of the insulin resistance phenotype, as it identifies a proportion of subjects with insulin resistance without directly measuring insulin action." (PMID 20374655, 2010). "Adipose tissue is not resistant to insulin in the early stages of whole-body insulin resistance, but muscle is resistant very early in the progression of metabolic syndrome X. Therefore, physical activity and yogasans, appear to be important in the prevention and treatment of insulin resistance." (PMID 20671994, 2010). "Although attenuation of insulin resistance by GLP-1 or AC3174 may contribute to this benefit, insulin-independent cardiac or extra-cardiac actions such as vasodilatation, renoprotection, and reduction of apoptosis may have also contributed to the reduction in mortality." (PMID 21080957, 2010). "Since NEFA released from adipose tissue has been proposed as a link between obesity and insulin resistance, the reduction of NEFA level resulted from Boc5 therapy may therefore be one possible mechanism responsible for the restoration of insulin sensitivity in obese animals." (PMID 21151924, 2010). "We have examined whether saturated nonesterified fatty acids (NEFA) and insulin, which increase in concentration with developing insulin resistance, can trigger the production of interleukin (IL)-6 and tumor necrosis factor (TNF)-α in human monocytes." (PMID 21054880, 2010). "That the relationship between AG and UAG may have an impact on metabolism has been suggested from clinical studies which show an indirect relationship between circulating AG/UAG ratio and insulin resistance, and a decreased AG/UAG ratio in fasting, relatively insulin sensitive, subjects." (PMID 20668691, 2010). "On the other hand, any pre-pregnancy data regarding insulin resistance was not available in our sample, even if it is likely to hypothesize that insulin levels were higher in PCOS subjects than in healthy controls also before pregnancy." (PMID 20942923, 2010). "As the O-GlcNAc modification has been detected on a number of proteins involved in the insulin signaling cascade, such as Akt, IRS-1, and FoxO1, elevated O-GlcNAc levels have the potential to be a molecular mechanism that links hyperglycemia to insulin resistance." (PMID 20851344, 2010). "It is interesting to note that while there is not a significant increase in the levels of circulating insulin, there is a discernable upward trend in UN animals that could indicate the initial stages in the establishment of insulin resistance." (PMID 19787071, 2009). "In this study, we did not assess Insulin levels and Insulin resistance of the subjects." (PMID 19948072, 2009). "Although not testable, this decrease could contribute to fight adipocyte insulin resistance by increasing resting glucose uptake in order to compensate the decreased adipocyte GLUT4 expression, a common feature of many insulin resistant states that we also observed in our partients." (PMID 19590752, 2009).
Insulin resistance (continued). "In addition, results show that 15 Hz EA on the bilateral Zusanli acupoints may improve insulin resistance by decreasing the plasma FFA levels and recovering the expression of insulin signal proteins (IRS1 and GLUT4), which enhances insulin activity." (PMID 19646276, 2009). "In relatives that have not developed insulin resistance, changes in gene expression are not secondary to an altered metabolic milieu since these individuals are not subjected to any metabolic dys-regulation or decreased level of insulin action." (PMID 19668377, 2009). "The purpose of this study is to evaluate whether or not EA stimulation can improve insulin sensitivity by decreasing plasma FFAs levels in steroid background rats with insulin resistance." (PMID 19646276, 2009). "Studies of the mechanism of insulin resistance of PCOS have found evidence of altered serine phosphorylation in the insulin receptors of cultured skin fibroblasts from PCOS patients, which inhibited IR activation by tyrosine autophosphorylation in response to insulin stimulation." (PMID 19169352, 2009). "We hypothesized that the insulin resistance that is present in critical illness would affect circulating adiponectin, RBP4, and leptin levels and that the improved insulin sensitivity that we observed in intensive insulin therapy (IIT) patients would change the adipokine levels." (PMID 19589139, 2009). "Our data differ from animal studies and suggest Syntaxin 4 content may not be involved in short-term regulation of insulin action in humans, and may not be important to obesity-induced insulin resistance." (PMID 18652694, 2008). "Although the details of the mechanisms of action could not be clarified, candesartan could improve insulin resistance and thus relieve glucotoxicity, improving insulin secretion." (PMID 18633754, 2008). "But these fatty acids do not show many PPAR effects such as reversing insulin resistance, which may occur due to dissociation between n-3 polyunsaturated fatty acid and lipid metabolism and insulin action in insulin resistant state." (PMID 18355413, 2008). "Insulin resistance was measured in a cohort of 37 non-diabetic patients undergoing cardiac surgery by assessment of insulin requirement to maintain euglycaemia and repeated measurements of an insulin glycaemic index." (PMID 19087258, 2008). "Due to the lower threshold to initiate insulin treatment, and the broadened exposure to insulin among patients without insulin resistance, patients (on average) received lower doses of insulin to control blood glucose in period III compared with the previous two periods." (PMID 18312617, 2008). "Previous studies have demonstrated that fasting insulin was highly correlated with homeostasis model assessment (HOMA) and quantitative insulin sensitivity check index (QUICKI) (correlation coefficients >0.95) of insulin resistance among nondiabetic individuals." (PMID 18307789, 2008). "Thus, the goal of this study was to determine whether altered insulin activation of the PI3K/Akt and MAPK signalling pathways could contribute to the development of insulin resistance and type 2 diabetes in LBW humans." (PMID 19011679, 2008). "In particular, insulin may not be a reliable marker for insulin resistance and subsequent atherosclerosis." (PMID 17958881, 2007). "All of this would strongly indicate that the metabolic syndrome is an exaggerated thrifty response, characterised by insulin resistance, which not only induces a propensity to store fat, but results in a fat-mass related activation of the APR (and resistance to its normal suppression by insulin)." (PMID 17531095, 2007). "The virtual flat line glucose and insulin response to a low-carbohydrate meal in the VLCARB group is remarkable data that clearly shows how effective this dietary pattern is at stabilizing the metabolic and hormonal milieu that is the goal for people with insulin resistance and type II diabetes." (PMID 16403234, 2006).
Insulin resistance (continued). "However, once differentiated, the adipocytes develop insulin resistance in the presence of GCs with decreased insulin-stimulated glucose uptake without changing their ability to bind insulin." (PMID 15689240, 2005). "Although a direct link between protein metabolism/ secretion and DIO/ insulin resistance is not as well established, in other insulin sensitive tissues the release of hormones and trafficking of receptors clearly plays a role in regulating tissue specific responses to insulin and glucose." (PMID 15985155, 2005). "Surgical removal of VAT may reduce insulin resistance and plasma insulin levels, while liposuction of SCAT does not confer metabolic benefits." (PMID 15530168, 2004). "To date, it has not yet been established that insulin resistance, i.e., resistance of cells to insulin's effects, is responsible for the onset of the multiple risk factors associated with insulin resistance syndrome and subsequent development of atherosclerosis and cardiac events." (PMID 15530168, 2004). "However, if compensated by increased insulin production, insulin resistance by itself does not lead to overt disease." (PMID 12745664, 2003). "To date, no studies have specifically evaluated the effect of chronic alcohol ingestion on insulin secretion or insulin resistance, although the study described previously by Ben and colleagues (1991) suggests that chronic alcohol exposure does not diminish insulin secretion." (PMID 15706798, 1998). "However, it should also be pointed out that our longitudinal data from cohorts of beta-C3-KO mice did not confirm that significant increase in serum insulin preceded increases in insulin resistance, and further work at earlier timepoints of this model will be needed to verify this." (PMID 41386533, 2026). "It has also been speculated that hyperinsulinism and/or insulin resistance might result in decreased betatrophin levels as a negative feedback mechanism, leading to increased insulin secretion under conditions of typical glucose homeostasis and insulin sensitivity." (PMID 40554659, 2025). "Moreover, high insulin level could only be found to be an important promoter of HOMA-IR-determined insulin resistance in participants without prior COVID-19 status in our context." (PMID 40273152, 2025). "In addition, Asian populations have been reported to develop insulin resistance and type 2 diabetes at lower levels of obesity than Caucasian populations, implying that the WC–insulin relationship may not be identical across ethnic groups." (PMID 41302993, 2025). "Finally, we calculated HOMA‐IR using baseline measurements of insulin and glucose, which may not accurately reflect insulin resistance over the entire 4‐year study period." (PMID 40955380, 2025). "Therefore, the reversible modulation of insulin, as well as leptin receptor phosphorylation and signaling, holds significant clinical promise, highlighting the potential of PTP1B inhibition to reduce insulin resistance, restore glycemic balance, and target both type 2 diabetes and obesity." (PMID 39941054, 2025). "Hence, this review will focus on the composition, biogenesis, and insulin signalling that facilitate GSV mobilization and trafficking, examining their regulation under healthy physiological conditions and the alterations that occur in the context of insulin resistance." (PMID 40806697, 2025). "In humans, healthy individuals with higher circulating leptin levels are often accompanied by lower insulin sensitivity independent of adiposity, suggesting that hyperleptinemia could be a compensatory response to insulin resistance, which might lead to more adverse effects on metabolic outcomes." (PMID 40066865, 2025). "A prospective analysis of a large cohort of generally healthy women showed that certain FFAs might affect the risk of developing GDM probably through the negative association with insulin resistance (measured as HOMA-IR) and insulin secretion (measured as C-peptide)." (PMID 40649117, 2025).